EGFR (epidermal growth factor receptor)
Diseases named in the same sentence as EGFR in open-access papers (continued):
Sharing a sentence is not in itself a finding about the gene and the disease.
colorectal cancer (continued). "By high-throughput i-CR drug screening, they discovered that inhibition of the EGFR and MEK or CDK4/6 pathways exerted a synergistic inhibitory effect against colorectal cancer and supersynergistic effects when EGFR, MEK, and CDK4/6 inhibitors were used simultaneously." (PMID 34150763, 2021). "EGFR overexpression could induce tumor cell EMT and then promote the progression and metastases of colorectal carcinoma." (PMID 34147083, 2021). "Interestingly, recent literature data, obtained in solid tumors including colorectal carcinoma, have suggested that both IL-15/IL-15α axis and TGF-β/SMAD-3 pathway are also involved in determining the effectiveness of the anti-EGFR agent, cetuximab." (PMID 33916844, 2021). "This strategy may also find application in other EGFR-positive tumours in which CTX has been ineffective, such as in KRAS mutant colorectal cancers." (PMID 32913288, 2020). "Point mutations in the KRAS gene are present in approximately 35–45% of colorectal cancers, and serve as a negative predictive factor of response to anti-EGFR therapy." (PMID 32300895, 2020). "We found that EGFR signaling activated IRE1α through EGFR-MEK-ERK pathway, inhibition of MEK or ERK could reduce the IRE1α phosphorylation and XBP1s expression in colorectal cancer cell lines." (PMID 32489465, 2020). "The Epidermal Growth Factor Receptor (EGFR)-targeting monoclonal antibodies (mAbs) cetuximab and panitumumab have been widely used for treatment of KRAS wild-type colorectal cancer, whereas the HER2-targeting antibody trastuzumab has been successful in HER2-amplified breast cancers." (PMID 31959764, 2020). "Consequently, targeting EGFR with mAbs or tyrosine kinase inhibitors (TKI) has been established in cancer therapy in e.g. NSCLC, colorectal cancer, head and neck cancer, or pancreatic cancer but therapy resistance occurs frequently and compromises outcome." (PMID 32903756, 2020). "In colorectal cancer cells, it was reported that PGE2 could transactivate EGFR, which can induce cell migration and invasion by elevating PI3K-Akt signaling." (PMID 32498447, 2020). "Accordingly, we instead employed the EGFR small-molecule inhibitor erlotinib of which efficacy for colorectal cancer was proved but not approved for clinical use due to the adverse events severer than cetuximab." (PMID 32708005, 2020). "Oncogenic mutation within the KRAS gene represents a negative predictor for treatment response to anti-epidermal growth factor receptor (EGFR) in patients with colorectal cancer." (PMID 33002027, 2020). "In colorectal cancer, absence of RAS mutations and sidedness were found to be better predictors of response than EGFR expression or amplification." (PMID 33364187, 2020). "In colorectal cancer, EREG serves as a biomarker of anti-EGFR therapy." (PMID 32596278, 2020). "In addition, AQP3 and epidermal growth factor receptor (EGFR) are both involved in the differentiation and metastasis of colorectal cancer, thus serving as a potential inhibition target." (PMID 32662230, 2020). "This study strongly supports the notion that EGFR protein expression in colorectal cancer is a negative prognosticator." (PMID 32155907, 2020). "The phase III MRC COIN trial showed no statistically significant benefit from adding the EGFR-target cetuximab to oxaliplatin-based chemotherapy in first-line treatment of advanced colorectal cancer." (PMID 31851321, 2020). "This association had been repeatedly reported in in vitro models and also found in melanoma cases, whilst not in colorectal cancer patients due to feedback activation of ERK-signalling mediated via EGFR." (PMID 33274713, 2020).
colorectal cancer (continued). "Targeted sequencing of individual genes to guide therapy has become the standard of care for several different cancer types, including colorectal cancer (KRAS, BRAF, and NRAS), lung cancer (KRAS and EGFR), melanoma (BRAF), GI stromal tumor (KIT), and gliomas (IDH1 and IDH2)." (PMID 32914008, 2019). "The targeting of activated epidermal growth factor receptor (EGFR) with therapeutic anti-EGFR monoclonal antibodies (mAbs) such as cetuximab and panitumumab has been used as an effective strategy in the treatment of colorectal cancer (CRC)." (PMID 31409052, 2019). "KRAS is an independent negative predictor for anti-epidermal growth factor receptor (anti-EGFR) treatment in colorectal cancers (CRCs)." (PMID 31729406, 2019). "Preclinical studies suggest that the lack of efficacy in BRAFV600E colorectal cancer is due to adaptive feedback reactivation of mitogen-activated protein kinase signalling, often mediated by epidermal growth factor receptor (EGFR)." (PMID 30792807, 2019). "In colorectal cancer, p38 MAPK activation can be driven by EGFR." (PMID 30478887, 2019). "Currently, there is no positive biomarker available for selection of cancer types that are favorable to anti-EGFR mAbs, although KRAS mutations are a negative predictor for anti-EGFR mAbs in treating colorectal cancer." (PMID 31508364, 2019). "EGFR levels remained unchanged in LoVo and HCT116 colorectal cancer cells." (PMID 30910997, 2019). "We found that there was inconsistency in the frequency distribution of CNAs in both of the data sets for those actionable genes from our list which are considered promising druggable targets for NSCLC, and colorectal cancer, such as KRAS, BRAF, EGFR, ATM, and PIK3CA." (PMID 30728399, 2019). "However, activating the EGFR and downstream ERK pathway by pinin facilitates cell proliferation, invasion, tumorigenic growth, and metastasis in colorectal cancer." (PMID 30487162, 2019). "Similarly, in the 3D colorectal cancer (CRC) cell lines that were cultured in laminin-rich-extracellular matrix conditions, the EGFR expression was decreased compared to 2D cultures." (PMID 30651721, 2019). "For EGFR negative colorectal cancer cell line SW620, RN765C had little effect and behaved just like the negative control ADC confirming the specificity of RN765C." (PMID 30323890, 2018). "The peculiar dependency of colorectal cancer on EGFR signaling does not seem to be related to the presence of EGFR abnormalities present in these tumors, but to the peculiar function of this receptor in the colon physiology." (PMID 29652830, 2018). "When the first anti-epidermal growth factor receptor (EGFR) antibody therapies for colorectal cancers were brought to the market by industry, there were no subpopulations identified." (PMID 29435448, 2018). "In addition to colorectal cancer cells, human gastric cancer NUGC4-RFP cells that overexpressed EGFR were used to investigate the efficacy of integrated 64Cu therapy with 64Cu-PCTA-cetuximab." (PMID 29989003, 2018). "In addition, EGFR signalling in colorectal cancer HCT116 cells, auto-phosphorylation of EGFR, and its downstream phosphorylation of AKT or ERK were all inhibited by PGRMC1 knockdown or by the addition of CO." (PMID 30087538, 2018). "The benefit of utilizing BRAF inhibitors does not apply to colorectal cancer due to the rapid feedback activation of EGFR." (PMID 30519549, 2018). "We coupled classic control siRNA that was labeled with Alexa 488 and/or Alexa 555, respectively to the anti-EGFR-antibody cetuximab via sulfo-SMCC-protamine and treated the colorectal cancer (CRC) cell lines DLD1, SW480 and HT29 with these antibody-siRNA complexes in vitro." (PMID 30001368, 2018). "Additionally, indirect TRAIL-induced pro-survival signaling via EGFR/HER2 has been reported in colorectal cancer cells, which provides further rationale for combination of TRAIL with EGFR- and HER2-blocking molecules." (PMID 29541416, 2018).
colorectal cancer (continued). "They confirmed that the new drug leads to reduced EGFR levels by degrading RAS and β-catenin and therefore suppresses the growth of colorectal cancer cells in samples with or without the resistant mutations." (PMID 30459318, 2018). "The third monoclonal antibody directed to surface receptors discovered in order of time is Cetuximab (Erbitux®) directed against the epidermal growth factor receptor (EGFR), frequently altered in numerous tumors, especially colorectal carcinomas, NSCLC and head and neck cancers." (PMID 30483135, 2018). "In the present study, we showed that the combination of GEF and SAL was synergistic at decreasing cell viability, colony formation ability and inducing cell apoptosis in colorectal cancer cell lines irrespective of their EGFR and KRAS status." (PMID 26461472, 2017). "We detected 477 (43%) colorectal cancer patients profiled in COSMIC V73 to have KRAS mutations, reflecting that almost half of CRC patients are not responsive to anti-EGFR antibody therapies." (PMID 28591715, 2017). "It was later found out that EGFR expression by IHC in colorectal cancer did not correlate with response to therapy, and subsequent investigation led to the identification of the KRAS mutation conferring resistance." (PMID 28030802, 2017). "In patients with colorectal cancer, EGFR therapy-resistant KRAS mutant subclones support non-mutant therapy-sensitive cells by secreting increased levels of TGFalpha and amphiregulin, in turn sustaining EGFR/ERK signalling in sensitive cells." (PMID 28716075, 2017). "Here, we showed the antibiotic salinomycin (SAL) combined with GEF exerted synergistic cytotoxicity effects in colorectal cancer cells irrespective of their EGFR and KRAS status, with a relatively low toxicity to normal cells." (PMID 26461472, 2017). "Similarly, the Fc-optimized anti-EGFR mAb imgatuzumab (Roche Glycart) is tested in Phase I/II clinical trials for head and neck cancer and in KRAS mutant colorectal cancer." (PMID 28620386, 2017). "Since SRC and EGFR appear to cooperate to increase tumorigenicity, dual inhibition of SRC and EGFR has been proposed, such as in head and neck squamous cell carcinoma and colorectal cancer." (PMID 28513565, 2017). "Here we show a carbon-based nanomaterial nanodiamond (ND) that carried paclitaxel (PTX), a microtubule inhibitor, and cetuximab (Cet), a specific monoclonal antibody against epidermal growth factor receptor (EGFR), inducing mitotic catastrophe and tumor inhibition in human colorectal cancer (CRC)." (PMID 28852020, 2017). "Finally, Cetuximab is a monoclonal antibody which binds to the epidermal growth factor receptor (EGFR) and is approved for use in RAS wt colorectal cancer." (PMID 28492495, 2017). "Patients with KRAS-mutant colorectal cancer do not benefit from EGFR-targeted therapy and outgrowth of KRAS-mutant cells accompanies onset of resistance." (PMID 27437872, 2016). "Indeed, recent research efforts have focused on the development of agents targeting the epidermal growth factor receptor (EGFR), which is frequently overexpressed in colorectal cancer and contributes cancer cell proliferation, metastasis, and angiogenesis." (PMID 26657506, 2016). "For colorectal cancer (CRC) patients, international guidelines made RAS (KRAS and NRAS) status a prerequisite for the use of anti-epidermal growth factor receptor agents (anti-EGFR)." (PMID 27999270, 2016). "Colorectal cancer with RAS wild type can be effectively treated with cetuximab, while it is known that patients with a K-RAS or N-RAS mutation do not respond to anti-EGFR treatment." (PMID 27252651, 2016). "Most importantly, the EGFR signalling cascade involving PI3K/AKT/mTOR and Raf/MEK/ERK pathways are particularly relevant, since they are commonly activated in several cancer entities, including colorectal cancer." (PMID 27095166, 2016).
colorectal cancer (continued). "An example is the expression of the Epidermal Growth Factor Receptor (EGFR), and the Vascular Endothelial Growth Factor Receptor (VEGFR) in colorectal cancer, that led to the clinical development of drugs against them, such as panitumumab or cetuximab against EGFR, and bevacizumab against VEGFR." (PMID 26418718, 2015). "The understanding of colorectal cancer (CRC) biology is rapidly growing and several molecular pathways including Wnt- β-catenin, TGF—β and epidermal growth factor receptor (EGFR) signalling have been identified that are deregulated at different stages of colon carcinogenesis." (PMID 25568935, 2015). "KRAS mutational status is considered a negative predictive marker of the response to anti-EGFR therapies in colorectal cancer (CRC) patients." (PMID 26110767, 2015). "Cetuximab is an antibody for epidermal growth factor receptor (EGFR), but there is no clear relationship between expression level of EGFR and tumor shrinkage in phase II clinical trial for EGFR expressing colorectal cancer." (PMID 25380636, 2015). "In BRAF-mutant colorectal cancer cells, BRAF keeps EGFR inactive." (PMID 25885672, 2015). "The opinion within the clinical setting is that the current recommendations for EGFR detection and determining cetuximab efficacy in colorectal cancer from these are not ‘fit for purpose’." (PMID 26149458, 2015). "In the context of EGFR inhibition in a wild-type KRAS colorectal cancer cell line we show that a lack of TK1 attenuation, and thus similar [18F]-FLT PET, in treated xenografts reflected PI3K-mTOR activity." (PMID 25247710, 2014). "Considering that RAS mutations in those codons have been reported to predict lack of response to anti-EGFR therapy in colorectal cancer, further studies are necessary to answer important questions about features across various RAS mutants." (PMID 24885062, 2014). "Our results show that KRAS-LCS6 genotype alone is not a meaningful predictor of outcome for colorectal cancer patients as a whole or for those with metastatic disease treated with anti-EGFR therapy." (PMID 24890702, 2014). "In conclusion, the results presented here demonstrate that dual inhibition of EGFR with erlotinib and cetuximab, combined with the VEGF antibody bevacizumab, is well-tolerated, allowing full doses of all three drugs in patients with colorectal cancer." (PMID 25594061, 2014). "Mutations in KRAS can be identified in 30-40% of colorectal cancers and mutated KRAS is constitutively active independent of EGFR signaling." (PMID 25551625, 2014). "We report that AboundTM was effective for a non-resectable colorectal cancer patient treated with an anti-EGFR antigen panitumumab who had developed skin disorder." (PMID 24517087, 2014). "Since, EGFR is capable of forming heterodimers with the other members of the HER (Human epidermal receptor) family, it is important to investigate the co-expression and prognostic significance of all members of the HER family in colorectal cancer patients." (PMID 24609222, 2014). "Multidisciplinary therapies, including systemic chemotherapy against unresectable and/or recurrent colorectal cancer, have improved, and FOLFOX, CapeOX and FOLFIRI combination chemotherapies plus bevacizumab or anti-EGFR monoclonal antibody can improve the survival times of patients." (PMID 24765155, 2014). "For example, activating BRAF mutations (e.g. V600E) have been associated with a benefit using vemurafenib in melanomas, but not in colorectal carcinomas due to the activation of EGFR pathway in colon cancer." (PMID 25415047, 2014). "KRAS status has emerged as a negative predictor of clinical benefit from anti-EGFR antibodies in colorectal cancer, and anti-EGFR antibodies use was limited to KRAS wild type tumors." (PMID 23935912, 2013). "In colorectal cancer, the presence of mutations in the KRAS gene indicates that the tumor will not respond to EGFR antibody therapy." (PMID 24280411, 2013).
colorectal cancer (continued). "The EGFR 3′ untranslated region (UTR) harbors a polyadenine repeat which is polymorphic (A13/A14) and undergoes somatic deletions in microsatellite instability (MSI) colorectal cancer (CRC)." (PMID 23565769, 2013). "In colorectal cancer, studies with NVP-AEW541 suggested that a combination therapy targeting both EGFR and IGF-1R could be a promising approach." (PMID 23525758, 2013). "In colorectal cancer, KRAS and BRAF mutations have been shown to identify a cluster of patients that does not respond to anti-EGFR therapies; the identification of these mutations is therefore clinically extremely important." (PMID 23536897, 2013). "Two studies detected the critical role of EGFR in BRAF V600E mutant colorectal cancer cells that did not respond to BRAF inhibition." (PMID 24298448, 2013). "In colorectal cancer, the demonstration that patients with KRAS mutated tumors did not benefit from anti-EGFR monoclonal antibodies was established independently of the technology used to identify KRAS mutated tumors." (PMID 23935912, 2013). "A phase II study of IMC-A12, another anti-IGF-IR antibody, alone and in combination with cetuximab in patients with colorectal cancer refractory to EGFR inhibitor did not demonstrate meaningful anti-tumor activity." (PMID 23921573, 2013). "In patients with colorectal cancer, responses to EGFR-targeted therapy appear to be independent of the level of EGFR expression." (PMID 22802884, 2012). "For instance, colorectal cancer patients who present mutations in KRAS or BRAF do not respond to panitumumab, a monoclonal antibody against EGFR, recently approved by FDA as a monotherapy against metastatic colorectal carcinoma." (PMID 23207070, 2012). "For example, in human epidermoid carcinoma HEp3 cells, α5 integrin binding to the epidermal growth factor receptor, EGFR, enhanced proliferation while in Caco-2 and HT-29 colorectal carcinoma cells, α5/EGFR binding resulted in EGFR lysosomal degradation followed by proliferation arrest." (PMID 22626691, 2012). "We analyzed the influence of 8 germinal polymorphisms of candidate genes potentially related to EGFR signalling (EGFR, EGF, CCND1) or antibody-directed cell cytotoxicity (FCGR2A and FCGR3A) on outcome of colorectal cancer (CRC) patients receiving cetuximab-based therapy." (PMID 22117530, 2011). "But since there are no guidelines, testing for EGFR gene amplification in colorectal cancer is not routinely performed." (PMID 21403829, 2011). "The failure of 3 large randomized trials to show benefit for irinotecan in the adjuvant treatment of colorectal cancer and the recent disappointing failure of anti-VEGF and anti-EGFR monoclonal antibodies to improve survival makes the search for effective new agents all the more urgent." (PMID 22168568, 2011). "Mutations in KRAS have recently become established as a negative predictive marker for the benefit of EGFR monoclonal antibodies in advanced colorectal cancer." (PMID 21811258, 2011). "Furthermore, we extended this analysis to examine the incidence of additional molecular events that have been proposed as candidate biomarkers for response to anti-EGFR agents in NSCLC and colorectal cancer." (PMID 21274259, 2010). "In colorectal cancer, there is no direct correlation between the amount of EGFR on the cell surface and the effects of EGFR blockade in vivo." (PMID 20565817, 2010). "EGFR is overexpressed in a variety of solid tumors, including colorectal cancer (CRC), squamous cell cancer of the head and neck, and non-small-cell lung cancer." (PMID 20680104, 2010).